HNRNPLL (heterogeneous nuclear ribonucleoprotein L like)
Description:
RNA-binding protein that functions as a regulator of alternative splicing for multiple target mRNAs, including PTPRC/CD45 and STAT5A. Required for alternative splicing of PTPRC.
Synonyms: HNRPLL; SRRF
Tractability: PROTAC: UniProt records ubiquitination sites on it; ubiquitination databases record sites on it; its protein half-life has been measured.
Gene: Protein-coding gene on chromosome 2 (38,561,969 to 38,603,586, reverse strand). Ensembl gene ENSG00000143889.
Subcellular location (Human Protein Atlas): Nucleoplasm; Cytosol; Mitochondria
Gene Ontology:
Molecular function: mRNA binding; protein binding; RNA binding; nucleic acid binding
Biological process: positive regulation of RNA splicing; mRNA processing; regulation of RNA splicing
Cellular component: membrane; nucleus; synapse
Genetic constraint (gnomAD): Loss-of-function variants: 8 observed, 16.92 expected, observed/expected ratio (o/e) 0.47, 90% interval 0.28 to 0.85. The upper end of that interval is the gene's LOEUF score, 0.85, which puts it in group 3 of 6, group 1 being the genes least tolerant of losing a copy. Missense variants: 310 observed, 348.1 expected, observed/expected ratio (o/e) 0.89, 90% interval 0.81 to 0.98. Synonymous variants: 156 observed, 131.51 expected, observed/expected ratio (o/e) 1.19, 90% interval 1.04 to 1.36.
Homologues: Orthologues: dog HNRNPLL (100% identical), guinea pig HNRNPLL (99% identical), rabbit HNRNPLL (98% identical), chimpanzee HNRNPLL (97% identical), mouse Hnrnpll (97% identical), rat Hnrnpll (96% identical), macaque HNRNPLL (96% identical), pig HNRNPLL (96% identical), tropical clawed frog hnrnpll (85% identical), Caenorhabditis elegans hrpl-1 (35% identical), Drosophila melanogaster sm (34% identical). Paralogues in human: HNRNPL (54% identical), PTBP1 (27% identical), PTBP2 (26% identical), PTBP3 (25% identical), RBM20 (20% identical).
Diseases named in the same sentence as HNRNPLL in open-access papers:
HNRNPLL is named in the same sentence as 12 diseases in open-access papers, as found by Europe PMC text mining. Sharing a sentence is not in itself a finding about the gene and the disease. The quoted sentences say what the papers report.
colorectal cancer (4 papers, 2017 to 2022). A primary or metastatic malignant neoplasm that affects the colon or rectum. "HNRNPLL, a tissue-specific heterogeneous nuclear ribonucleoprotein, has been shown to be related to progression of colorectal cancer (CRC)." (PMID 35832652, 2022). "HNRNPLL, an RNA-binding protein that participates in mRNA splicing and stability, was identified as a colorectal cancer metastasis suppressor." (PMID 32282333, 2020). "In summary, future studies will unleash the detailed molecular mechanisms of HNRNPLL on the regulation of cancer progression and provide a way for targeting the early events in the colorectal cancer metastasis." (PMID 29085822, 2017). "HNRNPLL regulates AS of CD44 to promote proliferation and metastasis of colorectal cancer." (PMID 33976726, 2021).
colon cancer (2 papers, 2017 to 2018). "HNRNPLL expression was downmodulated when colon cancer cells were induced to undergo the epithelial–mesenchymal transition." (PMID 29652830, 2018). "In summary, their data provide the critical role of HNRNPLL in regulating tumor cell invasion and epithelial-mesenchymal transition to regulate metastasis of colon cancer cells." (PMID 29085822, 2017). "Further, knocking down HNRNPLL inhibits in-vivo primary tumor growth, and lung metastasis of colon cancer which is reverted by shRNA resistant HNRNPLL plasmid." (PMID 29085822, 2017). "Despite these, the exact mechanism of how and when HNRNPLL expression is lost or suppressed, during colon cancer progression remains to be characterized." (PMID 29085822, 2017). "shRNA mediated silencing of HNRNPLL inhibits in-vitro cell proliferation and enhances matrigel invasion to promote metastasis in colon cancer cells." (PMID 29085822, 2017). "Moreover, knocking down HNRNPLL promotes CD44v6 mediated HGF induced c-Met phosphorylation to promotes invasion in colon cancer cells." (PMID 29085822, 2017). "Using a genome-wide silencing approach in non-metastatic CMT93 mouse cell line expressing Venus fluorescent protein in a syngeneic mouse model, Sakuma and colleagues have delineated the inverse relationship between HNRNPLL and CD44v6 expression in the metastasis of colon cancer." (PMID 29085822, 2017). "Moreover, how expression level of HNRNPLL in a large cohort will serve as a prognostic marker and whether HNRNPLL expression can be used as tools for predicting drug treatment for colon cancer metastasis needs to be determined." (PMID 29085822, 2017). "Heterogeneous nuclear ribonucleoprotein L-like (HNRNPLL), a pre-mRNA splicing factor, is a metastasis suppressor gene; its knockdown in colon cancer cells enhanced their tissue invasiveness and their metastatic potential and induced increased expression of CD44v6." (PMID 29652830, 2018). "Further, given its critical importance in EMT transition, it will be plausible to see whether HNRNPLL regulates CSC growth, self-renewal, and drug resistance in colon cancer." (PMID 29085822, 2017).
breast carcinoma (1 paper, 2021). "Among all the RBPs (HNRNPU, HNRNPK, RBM5, HNRNPLL, HNRNPH1, HNRNPM, HNRNPA2B1) screened, only SRSF7 (also known as 9G8) was substantially upregulated in hypoxia-treated breast cancer cells." (PMID 34362878, 2021).
cerebral atherosclerosis (1 paper, 2021). Atherosclerosis of the cerebral vasculature. "Notably, CNOT3 protein has evidence for physical interactions in the BioGRID dataset with two proteins we previously found associated with cerebral atherosclerosis in human brain, HNRNPLL and RTF1." (PMID 34073619, 2021).
glioma (1 paper, 2022). A benign or malignant brain and spinal cord tumor that arises from glial cells (astrocytes, oligodendrocytes, ependymal cells). "We also discovered that the SFs NOVA1, HNRNPC, HNRNPLL, and RBM4 are independent risk factors that affect the prognosis and immune cell infiltration of patients with glioma." (PMID 35832652, 2022). "Our study found that genes involved in AS events affected glioma survival including NOVA1, HNRNPC, HNRNPLL, RBM4." (PMID 35832652, 2022). "We demonstrated that NOVA1, HNRNPC, HNRNPLL, and RBM4 were independent prognostic factors for glioma, and their expression was verified by western blotting analysis." (PMID 35832652, 2022). "We speculate that, unlike the effect of HNRNPLL in CRC, the overexpression of these four SFs may facilitate glioma metastasis but suppress glioma cell proliferation." (PMID 35832652, 2022).
liver cancer (1 paper, 2026). An epithelial or non-epithelial malignant neoplasm that arises from the liver. "Functional experiments demonstrated that HNRNPLL knockdown suppressed proliferation, migration, and invasion of liver cancer cells and inhibited tumor growth in vivo." (PMID 42042880, 2026).
ovarian carcinoma (1 paper, 2021). A malignant neoplasm originating from the surface ovarian epithelium. "Because many studies have reported that ABCG1 regulates intracellular cholesterol homeostasis mainly by affecting cholesterol efflux, we also tested the total cholesterol levels and cholesterol efflux in ovarian cancer cells overexpressing ECM1a, ECM1b, ABCG1, and hnRNPLL." (PMID 34244494, 2021). "Therefore, selectively targeting hnRNPLL, SRSF1, and SRSF6 may usher in an important new era of ovarian cancer treatment." (PMID 34244494, 2021). "Nevertheless, the results of our clinical analyses showed that ECM1a, integrin αXβ2, hnRNPLL, and ABCG1 were positively correlated with each other and that these molecules may be independent prognostic factors for poor survival in patients with ovarian cancer." (PMID 34244494, 2021).
plasmacytoma (1 paper, 2015). Plasmacytoma is a localized mass of neoplastic monoclonal plasma cells that represents approximately 5% of all plasma cell neoplasms. "However, the ratio of membrane Ighg2b to secreted Ighg2b was surprisingly reduced in a mouse plasmacytoma cell line that lacked hnRNPLL." (PMID 26703587, 2015).
tumor (7 papers, 2017 to 2026). "In addition, HNRNPLL expression was correlated with immune cell infiltration, tumor mutational burden, microsatellite instability, ferroptosis-related genes, and m6A methylation regulators." (PMID 42042880, 2026). "Multi-label immunohistochemistry (IHC) showed that tumor tissues injected with ASO exhibited fewer HNRNPLL, phospho-AKT, and phospho-mTOR positive cells." (PMID 37461053, 2023). "Delivery of an hnRNPLL-specific shRNA into A8i-A cells or transfection of hnRNPLL cDNA into A8i cells repressed or enhanced 3D culture growth, tumor growth, and ECM1a, pAKT, pFAK, pPaxillin and pRac expression, respectively." (PMID 34244494, 2021). "Moreover, immunostaining analysis of tumor samples shows the substantially decreased expression of HNRNPLL at the invasive front with E-cadherin suggesting its function in regulating early event in metastasis." (PMID 29085822, 2017). "Further immunoprecipitation assays showed that circZFR protected HNRNPLL from ubiquitination-mediated protein degradation, and thus, tumor-upregulated circRNAs could function as stabilizers of oncoproteins, expanding the horizon of post-transcriptional regulation in cancer." (PMID 37461053, 2023). "Thus, we conclude that circZFR enhances HNRNPLL protein stability by blocking ubiquitination and thereby elevated HNRNPLL protein levels mediate OXPHOS and tumor growth in LUAD." (PMID 37461053, 2023).
cancer (4 papers, 2021 to 2023). A tumor composed of atypical neoplastic, often pleomorphic cells that invade other tissues. "All of our data suggest that ECM1a plays a tumorigenic role and confers cancer cell cisplatin resistance through integrin αXβ2/hnRNPLL/ABCG1-mediated cellular phosphorylation signaling and stemness induction." (PMID 34244494, 2021).
heart disease (1 paper, 2021). "Further potentially disease-relevant protein candidates without a known functional relation to hypertrophy, fibrosis or decompensated heart disease were SLTM, HNRNPLL, FIP1L1, RNMT, KRT18 and PUF60 and the downregulated NUDT4, GCAT, KIDINS220 and ARVCF." (PMID 34937869, 2021).
HNRNPLL also shares sentences with these, for which no sentence is quoted: hepatocellular carcinoma (1 paper).